MICA (MHC class I polypeptide-related sequence A)
Diseases named in the same sentence as MICA in open-access papers (continued):
Sharing a sentence is not in itself a finding about the gene and the disease.
viral infection (32 papers, 2010 to 2023). "According to these reports, MICA is associated with viral infections, including human cytomegalovirus (HCMV), Epstein-Barr virus (EBV), hepatitis B virus (HBV), and severe acute respiratory syndrome corona virus 2 (SARS-CoV-2)." (PMID 37784183, 2023). "Malignant transformation or viral infection of the cells induce surface NKG2D ligands (MICA and MICB) expression that makes cancer cells susceptible to immune destruction." (PMID 37761005, 2023). "In addition, MICA upregulation is often associated with osmotic and oxidative stress, viral infections, and increased cell proliferation, which cannot be explained by DNA damage." (PMID 37784183, 2023). "Both variants may confer advantages and disadvantages in certain situations, such as virus infections, suggesting balancing evolution of MICA alleles." (PMID 26483398, 2015). "DNA damage, heat, viral infection and inflammation promote the expression of MICA, which triggers the activation of lymphocytes for immune responses." (PMID 34208618, 2021). "MICA expression is induced in response to various types of stress such as heat, DNA damage, and viral infection." (PMID 32245188, 2020). "It has been reported that DNA damage response pathways, heat shock stress, BCR/ABL oncogene, and bacterial/viral infections can all participate in regulating MICA/B expression." (PMID 31088566, 2019). "Their combined results demonstrate that viral infections efficiently induce MICA transcription in infected cells, and thereby mediate activating NKG2D signaling." (PMID 29867932, 2018). "Under conditions of cellular stress like in the course of viral infections or malignant transformations, it is significantly upregulated, defining the MICA/NKG2D axis important for immune surveillance." (PMID 29867932, 2018). "In kidney allografts, an enhanced MICA expression has been reported on epithelial and endothelial cells in response to ischemia-reperfusion injury, acute rejection, or viral infection." (PMID 29867932, 2018). "As a potent activating receptor, the NKG2D receptor plays an important role in the control of viral infections and tumorigenesis through recognizing its ligands, including MICA, MICB and ULBP1-4 in humans and Rae-1, H60 and MULT1 in mice." (PMID 27528231, 2016). "MHC class I polypeptide-related chain A (MICA) molecule is induced in response to viral infection and various types of stress." (PMID 23024757, 2012). "VSV has an interest in keeping NKG2D-ligands away from the cell surface, especially since the virus infection leads to a robust induction of MICA mRNA." (PMID 21857986, 2011). "MICA is expressed on the cell surface of the epithelial cells, fibroblasts, keratinocytes, endothelial cells, and monocytes under stress conditions, such as a virus infection." (PMID 35805975, 2022). "In viral infections, downregulation of MICA prevents recognition by NK cells." (PMID 35254093, 2022). "Nevertheless, virus infections can interfere with MICA expression." (PMID 35805975, 2022). "The increase in MICA levels is observed during viral infections, heat shock, and DNA damage." (PMID 36547538, 2022). "MICA has been attributed to autoimmune diseases and viral infection." (PMID 31718558, 2019). "Viral infections result in a strong induction of MICA expression." (PMID 29867932, 2018). "TCRγ1/TCRδ1 (alternatively termed Vγ1Vδ1) heterodimers have specificity for MHC Class-I chain-related A (MICA), a molecule participating in evasion of immune surveillance following viral infection and expressed on tumor cells as it is involved in the cellular stress response." (PMID 25566249, 2014). "While MICA is post-translationally dependent on the cell context or the status of viral infection, MICA may be readily processed from the cell surface in HBV-replicating primary hepatocytes and mainly released as soluble protein." (PMID 25026299, 2014).
viral infection (continued). "MICA protein has been considered as a stress marker of gastrointestinal epithelial cells because of its induced expression by several external stimuli such as heat, DNA damage, and viral infections." (PMID 23024757, 2012). "Cellular distress such as viral infections could lead to transport of cytoplasmic MICA to the cell surface." (PMID 20844584, 2010). "The roles MICA molecules may play in virus infection and tumor immunology have beenhighlighted." (PMID 22475346, 2012). "The small changes in driver proteins between the networks are seen in immunoregulatory proteins that are typically upregulated during viral infection (such as TRIM51 and MICA) and many of the proteins identified in the controllability analyses." (PMID 32993136, 2020). "Since both viral infection and malignant transformation induce expression of the immune activating NKG2D ligands MICA and MICB, we screened for the respective mRNA expression among 75 MCC tumors from 61 patients and a number of MCC cell lines." (PMID 26902929, 2016). "Given that the MICA/NKG2D signalling system is critically embedded in the innate and adaptive immune responses, it is particularly involved in the surveillance of cancer and viral infections." (PMID 37784183, 2023). "Expression of the stress-induced ligands MICA, MICB and ULBP 1–6 are up-regulated as a cellular response to DNA damage, excessive proliferation or viral infection; thereby, they enable recognition and annihilation by immune cells that express the powerful activating receptor NKG2D." (PMID 26982091, 2016). "Therefore, due to viral infections and long-term inflammation, MIC proteins (MICA and MICB) can be over-expressed." (PMID 25626490, 2015). "The production of MICA and MICB by virus-infection or tumor cells has been previously reported, and the ability of these ligands to induce cytotoxic activity in NK cells and other cytotoxic lymphocytes through the interaction with their cognate receptor, NKG2D, has been well established." (PMID 21477352, 2011). "Importantly, a previous study has reported that MICA protein is absent from most cells, but can be induced by viral infection, with its expression being frequent in epithelial tumours." (PMID 28505207, 2017).
autoimmune disease (26 papers, 2009 to 2025). A disorder resulting from loss of function or tissue destruction of an organ or multiple organs, arising from humoral or cellular immune responses of the individual to their own tissue constituents. "Taken together, our data indicate that the various MICA alleles have distinct roles in the development of diverse autoimmune diseases in Taiwanese people." (PMID 38474281, 2024). "The MICA gene is reported to be associated with autoimmune diseases, including systemic lupus erythematosus, autoimmune type 1 diabetes mellitus (T1DM), and patchy alopecia areata." (PMID 33017098, 2020). "MICA/B gene polymorphisms, expression levels and the amount of soluble MICA/B in the serum have been linked to autoimmune diseases, infections, and cancer." (PMID 32153595, 2020). "Many investigators have demonstrated that the MICA*A5.1 allele is associated with autoimmune diseases." (PMID 33017098, 2020). "Numerous studies have identified MICA polymorphisms to be associated with various malignant and autoimmune diseases." (PMID 26585323, 2016). "The variable affinity of NKG2D for MICA may influence receptor activation in predisposed individuals, which has been observed in various autoimmune diseases." (PMID 40458406, 2025). "The mechanisms underlying the effects of MICA alleles on the pathogenesis of autoimmune diseases may involve differences in MICA expression levels and avidity for NKG2D among MICA alleles." (PMID 38474281, 2024). "This scenario has been found in patients with autoimmune disease, such as systemic lupus erythematosus; the magnitude of this response may rely on the specific MICA variant, which may possibly result in increased tissue damage." (PMID 38146340, 2023). "While one can doubt why these innate immune response elements be important to understand the autoreactivity in PsA, the fact is that MICA and B polymorphisms are related to the genetic risk in other autoimmune diseases such as celiac disease, RA, and multiple sclerosis (MS)." (PMID 33581710, 2021). "In particular, the MICA*A5.1 polymorphism has been associated with cervical neoplasia, hepatocellular carcinoma, breast cancer, oral squamous cell carcinoma, and autoimmune diseases." (PMID 33017098, 2020). "Furthermore, constitutive MICA expression is associated with increased inflammation and autoimmune diseases." (PMID 32849657, 2020). "Dysregulation of the signalling pathway mediated by MICA molecules may trigger self-aggression and promote proinflammatory process underlying the development of autoimmune diseases." (PMID 32123296, 2020). "Additionally, associations between MICA alleles and thyroid disease and Addison’s disease have been observed, pointing to these factors of innate immunity contributing to the pathogenesis of autoimmune disorders." (PMID 28926962, 2017). "Although the significance of the polymorphism of MICA and MICB remains ill-defined, associations between alleles and autoimmune diseases and cancer has been widely reported." (PMID 34394116, 2021). "Many of these studies implicate a role of MICA in various malignant, infectious, or autoimmune diseases." (PMID 32582150, 2020). "Increased MICA expression has also been reported in autoimmune diseases, such as type 1 diabetes, celiac disease, rheumatoid arthritis, and atherosclerosis, where it is found on vascular endothelial cells." (PMID 28926962, 2017). "Increased MICA expression has been reported in tissues with inflammation and autoimmune diseases such as type 1 diabetes, celiac disease, rheumatoid arthritis, in atherosclerosis, where it is found on vascular endothelial cells, and in asthma." (PMID 28926962, 2017). "Antibodies against MICA were detected in samples from 41.7% of patients with celiac disease but in only 3.5% of those from controls (P <0.0001) and 8.2% from patients with autoimmune disease (P <0.0001)." (PMID 24565339, 2014).
autoimmune disease (continued). "We tested serum samples from 383 patients with celiac disease, obtained before they took up a gluten-free diet, 428 patients with diverse autoimmune diseases, and 200 controls for anti-MICA antibodies." (PMID 24565339, 2014). "A negative effect of the MICA rs1051792 A allele was also observed in the context of autoimmune disease." (PMID 41153412, 2025). "Although both MICA and TNFA genes have a high degree of polymorphism, and their allelic diversity has been reported in association with some autoimmune diseases, including psoriasis and with response to anti-TNF treatment, rs2523497 and rs1800610 have never been associated with psoriasis condition." (PMID 36423071, 2022). "The result of a weak MICA-129val interaction could lead to an increased expression of NKG2D as in autoimmune diseases, and favor interactions with other ligand binding proteins such as UL16-binding proteins (ULBPs)." (PMID 34489964, 2021). "The existence of MICA-null haplotypes in individuals without particular susceptibility to infectious or autoimmune diseases or cancer indicates some redundancy in the biological function of MICA." (PMID 34394116, 2021). "MICAgen mice do not only provide unlimited material for in vitro studies of MICA induction but also allow to study MICA regulation and induction in vivo using genetically-altered mouse models, treatment with small molecules or carcinogens, or by inducing autoimmune diseases." (PMID 32582150, 2020). "Moreover, the deleterious role of MICA rs1051792 GG genotype was reported in subjects diagnosed with another autoimmune disease—ulcerative colitis (UC)." (PMID 32123296, 2020). "The development of anti-MICA antibodies could be related to a gluten-containing diet, and seems to be involved in the development of autoimmune diseases in patients with celiac disease, especially younger ones." (PMID 24565339, 2014). "Deregulation of MICA expression has been implicated in the pathogenesis of rheumatoid arthritis and other T cell-mediated autoimmune diseases; therefore it should not be surprising that these genes have a role in the pathogenesis of PsA." (PMID 24600518, 2014). "Anti-MICA-positive patients had a higher risk of autoimmune disease than MICA antibody-negative patients (P <0.0001; odds ratio = 6.11)." (PMID 24565339, 2014). "With respect to tissue subjected to stress, the recognition of MICA by cells expressing NKG2D might participate in the induction of autoimmune diseases." (PMID 23209462, 2012). "Furthermore, MICA*A9 has a relation with autoimmune disease." (PMID 35805975, 2022). "Finally, we found that the associated risk of developing additional autoimmune diseases was 16 and 10 times as high in pediatric patients and adults with anti-MICA, respectively, as in those without." (PMID 24565339, 2014). "Various hypotheses have been proposed to explain the role of MICA in autoimmune diseases." (PMID 23209462, 2012). "HCP5 is a vital lncRNA between the MICA and MICB genes in the MHC I region and is involved in many autoimmune diseases, including malignant tumors." (PMID 35571053, 2022). "Additional immune-regulatory loci include MICA/MICB, CTLA4, PTPN22, CIITA, CLEC16A, CD274 (PD-L1), and NLRP1 (NALP1)—variants shared with other autoimmune diseases, underscoring common immune checkpoints rather than AAD-specific genes." (PMID 41465179, 2025). "Further, the effects of MICA alleles on modifications in serology tests, such as anti-cyclic citrullinated peptide (anti-CCP) positivity and clinical manifestations of autoimmune diseases, were not analyzed." (PMID 38474281, 2024). "The source gene of lnc-HCP5 is located between MICA and MICB genes, which regulates the activities of various immune cells such as B cells, lymphocytes and NK cells, and plays an important role in HIV, AIDS, and various autoimmune diseases." (PMID 33194692, 2020).
autoimmune disease (continued). "Accordingly, NKG2D and NKG2D-L are important therapeutic targets in the treatment of autoimmune disorders by blocking the interaction between NKG2D of immune cells and MICA on non-immune cells." (PMID 38474281, 2024).
pancreatic cancer (22 papers, 2011 to 2025). "Further, our findings of a positive association between the A5.1 polymorphism and pancreatic cancer risk are concordant with biological mechanisms explaining MICA shedding into circulation and its interaction with immune cells." (PMID 31166958, 2019). "In a multivariate model, having at least one copy of the MICA A5.1 allele was associated with an increased risk of pancreatic cancer." (PMID 31166958, 2019). "In this population-based case-control study, we found that having at least one copy of the MICA A5.1 allele was associated with an increased risk of pancreatic cancer." (PMID 31166958, 2019). "We also showed that participants with the MICA A5.1 allele had elevated circulating levels of s-MICA, in both controls and pancreatic cancer cases, with higher levels in the cases." (PMID 31166958, 2019). "Association between the genotype distribution of the MICA A5.1 polymorphism (dominant and additive models) and pancreatic cancer risk." (PMID 31166958, 2019). "Our data demonstrates that VPA enhances the susceptibility of pancreatic cancer cells to NK cell-mediated cytotoxicity both in vitro and in vivo by upregulating the expression of MICA and MICB via activation of the PI3K/Akt pathway." (PMID 24885711, 2014). "VPA enhances the susceptibility of pancreatic cancer cells to NK cell-mediated cytotoxicity both in vitro and in vivo by upregulating the expression of MICA and MICB via a PI3K/Akt signaling pathway-dependent mechanism." (PMID 24885711, 2014). "In addition, we reported that the association between the MICA A5.1 allele and pancreatic cancer disappeared after adjusting for s-MICA levels implying that the s-MICA was on causal pathway between MICA A5.1 allele and pancreatic cancer." (PMID 31166958, 2019). "Our study suggests higher risk of pancreatic cancer among those with the MICA A5.1 polymorphism, which may be explained by an increase in s-MICA secretion and impaired immune response." (PMID 31166958, 2019). "We hypothesized that the presence of the A5.1 polymorphism in the MICA gene, which encodes a truncated MICA protein, is associated with higher s-MICA levels and increased pancreatic cancer risk." (PMID 31166958, 2019). "Our findings of higher s-MICA levels and increased pancreatic cancer risk in participants with the MICA A5.1 polymorphism may be explained by changes in the s-MICA A5.1 protein, as a result of the polymorphism." (PMID 31166958, 2019). "MICA alleles and s-MICA levels were measured in 121 pancreatic cancer cases and 419 controls." (PMID 31166958, 2019). "Research has revealed that high glucose levels can enhance the expression of polycomb protein Bmi1, leading to increased GATA2 levels and suppression of cell surface MICA/B expression, thereby facilitating immune evasion in pancreatic cancer cells." (PMID 38879709, 2024). "The expression of HIF-1α in tumor cells under normoxia resists cytotoxic T lymphocytes (CTLs) and induces immune escape of pancreatic cancer cells from NK cells through the shedding of MICA, which interacts with NK-activating receptor (NKG2D)." (PMID 35283421, 2022). "In the hyperglycemia microenvironment, high glucose protects pancreatic cancer cells from natural killer cell (NK)-mediated killing by inhibiting the expression of MHC class I chain-related protein A/B (MICA/B), and promotes the immune escape of cancer cells." (PMID 33546519, 2021). "In this study, we demonstrated that high glucose inhibited the cell surface expression of MICA/B on pancreatic cancer cells and weaken the cytotoxicity of NK cells on pancreatic cancer." (PMID 31088566, 2019). "Treatment with A-769662 or AICAR increased p-AMPK expression, decreased Bmi1 expression, and increased MICA/B expression in pancreatic cancer cells." (PMID 31088566, 2019). "In current study, we confirmed that Bmi1 can inhibit anticancer immunity of pancreatic cancer via reducing NK cell killing through suppressing MICA/B expression." (PMID 31088566, 2019).